APOBEC3G (apolipoprotein B mRNA editing enzyme catalytic subunit 3G)
Diseases named in the same sentence as APOBEC3G in open-access papers (continued):
Sharing a sentence is not in itself a finding about the gene and the disease.
infection (83 papers, 2004 to 2025). The state of being infected such as from the introduction of a foreign agent such as serum, vaccine, antigenic substance or organism. "The HIV-1 Vif protein counteracts viral hypermutation caused by the host cytidine deaminase APOBEC3G (A3G), ensuring productive infection." (PMID 41280050, 2025). "The HIV-1 accessory proteins Vif, Vpu, and Nef can promote infection by overcoming the inhibitory effects of the host cell restriction factors APOBEC3G, Tetherin, and SERINC5, respectively." (PMID 34140527, 2021). "Some factors act before integration to inhibit viral entry (IFITM1-3 and transcription (TRIM5a, APOBEC3G) thus preventing spread and infection of bystander cells." (PMID 33872331, 2021). "Studies have reported high levels of ISG expression in CD4 T cells very early during infection, and increased levels of APOBEC3G was found to correlate with lower levels of infection in macrophages during SIV infection." (PMID 29520278, 2018). "Tetherin and APOBEC3G showed significantly higher expression levels in the stHIV-1sv infected macaques during the first 4 wpi, with APOBEC3G maintaining high levels throughout infection, indicating an important role in controlling virus replication." (PMID 30210504, 2018). "Our previously published data showed that the post-entry inhibition occurred at an early stage of infection and required induction of the host restriction factor APOBEC3G." (PMID 28509877, 2017). "Over-expression of APOBEC3G alone is sufficient for suppressing virus replication in T cell-based spreading infection experiments." (PMID 24986077, 2014). "It is possible that the down modulation observed is mediated by the virus in an attempt to facilitate the establishment of infection, similar to that seen for APOBEC3G and SAMHD1." (PMID 24410916, 2014). "Upon infection of these mutant-expressing cells, APOBEC3G mRNA levels were reduced compared to control cells to a similar extent that was observed for the IFNβ gene." (PMID 19371434, 2009). "APOBEC proteins and in particular APOBEC3G can provide potent intrinsic immunity to infection by viruses whose life cycle involves a single-stranded DNA step." (PMID 18577210, 2008). "Surprisingly, APOBEC3G expression during particle production only marginally inhibited HERV-KCON(VSV-G) infection, while APOBEC3F more potently reduced infectivity, reducing titers by about 50-fold." (PMID 17257061, 2007). "In this study, we have demonstrated that overexpressed as well as endogenous APOBEC3G were incorporated into HTLV-1 virions and that APOBEC3G inhibited the infection of HTLV-1." (PMID 15943885, 2005). "First, we confirmed the function of endogenous APOBEC3G in MT-2 cells by infection with HIV-1 wild type (WT) and ΔVif virions." (PMID 15943885, 2005). "We believe that selections like the one devised here will be applicable to the isolation of suppressors of other blocks to infection, including the prototypical Fv1 gene, the APOBEC3G cytosine deaminase, and the TRIM5a gene." (PMID 15453907, 2004). "Indeed, the infection of A3.01 cells, which express sub-lethal levels of APOBEC3G, allows for replication of Vif-defective virus expressing Vpr." (PMID 31652959, 2019). "However, in the case of HIV-1, it has been shown that APOBEC3G inhibits infection in two previous steps of the viral cycle." (PMID 31708924, 2019). "DENV-infection of DCs induced expression of ISGs MxA, APOBEC3G, ADAR1 and TRIM5α 24 h.p.i.." (PMID 29186193, 2017). "This suggests that at least partial antagonism of APOBEC3G may be a pre-requisite to natural cross-species infection." (PMID 26394054, 2015). "Furthermore, previous reports have shown AID and APOBEC3G to activate the DNA damage response upon infection with Ab-MLV and HIV, respectively, resulting in NKG2D ligand induction." (PMID 24244169, 2013). "This could result in APOBEC3G being packaged into virions after first round infection and contributing to the total inhibition." (PMID 20975956, 2010).
infection (continued). "Interestingly, there appears to be a correlation between the intracellular configuration of APOBEC3G and the cell's sensitivity to infection." (PMID 18577210, 2008). "APOBEC3C and APOBEC3G levels were higher in MCPyV+ MCCs compared with MCPyV− MCCs, and APOBEC3G showed statistically significant coexpression with LT, which could implicate an immune response to MCPyV infection and make APOBEC3C and APOBEC3G potential LT mutators." (PMID 36970060, 2022). "Moreover, we found that APOBEC3A and APOBEC3G used different mechanisms to block infection in vivo." (PMID 24851906, 2014). "Indeed, infection of macaques with these viruses revealed that Vif-mediated counteraction of APOBEC3G function is central to cross-species tropism but that other IFN-induced factors may also play important roles in controlling replication." (PMID 23825473, 2013). "The mRNA levels of APOBEC3G, ISG-15, RIG-I, IFN-α, and IFN-β were significantly enhanced in the mice infected with rt269I on 4 days post-infection." (PMID 31402915, 2019). "Since APOBEC3G is an inhibitor of HBV replication, a decrease in its intracellular level favors the infection." (PMID 29483904, 2018). "Finally, Vif-APOBEC3G antagonism in natural host switches suggests that at least partial antagonism of APOBEC3G may be a pre-requisite to natural cross-species infection." (PMID 26394054, 2015). "Localised productive infection triggered a broad innate response, with type-1 interferon sensitive IRF-7, STAT-1, TRIM5α and ApoBEC3G genes all upregulated during the acute phase but induction did not prevent viral persistence." (PMID 25162725, 2014). "To explore this hypothesis, we performed infection assays in CD4+ T cells using free viral particles and evaluated the transcriptional expression of the viral restriction factors SAMHD1, TRIM5, and APOBEC3G." (PMID 35802715, 2022). "These cells could produce higher amounts of other antiviral proteins in response to virus such as those observed in this study: MX2, TRIM22, APOBEC3G, and of immunoregulators such as ERAP2, further preventing productive infection." (PMID 28243241, 2017). "ApoBEC3G and TRIM5α mRNAs were upregulated during acute SIVmacC8 infection, though not in all tissues." (PMID 25162725, 2014). "Curiously, APOBEC3G-mediated inhibition of integration leads to a two-fold reduction in 2-LTR circles upon infection with a Δ-vif virus when compared controls lacking APOBEC3G." (PMID 21722380, 2011). "For example, HIV is known to alter the composition and function of EVs, leading to the secretion of infection-promoting host proteins such as virus receptors CCR5 and CXCR4, metalloprotease ADAM17 and other proinflammatory factors, and host restrictive factors such as APOBEC3G and TRIM5α." (PMID 37396389, 2023). "However, only Vif-expressing WT virus but not Vif-defective virus reduced levels of endogenous APOBEC3G during the course of infection (our own unpublished data)." (PMID 31652959, 2019). "The up-regulation of interferon related genes like APOBEC3G and APOBEC3F, as well as HIV-1 specific cytotoxic T-cell and neutralizing antibody responses might contribute to inhibit viral replication in the acute phase of infection." (PMID 30210504, 2018). "Unlike APOBEC3G and TRIM5α, tetherin does not represent an absolute block to infection, but may serve to attenuate virus replication in the absence of effective viral countermeasures." (PMID 19436700, 2009). "Therefore, we investigated expression of IL-15 and ISGs, such as APOBEC3G, ISG15, ISG20, MX1, MX2, and RSAD2, after infection with R5-tropic, non-opsonized (HIV) and complement-opsonized (HIV-C) HIV-1 strains (BaL and YU-2)." (PMID 34634939, 2021).
cancer (36 papers, 2007 to 2025). A tumor composed of atypical neoplastic, often pleomorphic cells that invade other tissues. "Furthermore, compared with the normal HMECs, the loss of promoter activity at the APOBEC3C, APOBEC3F, and APOBEC3G genes was specifically detected in the ER+ cancer cell." (PMID 26682542, 2015). "The deamination-independence of the restriction mechanism suggests that a catalytically inert APOBEC3G protein, such as E259Q, may be equally potent and simultaneously reduce the risk of cancer-promoting mutagenesis." (PMID 17849022, 2007). "Notably, APOBEC3G has been implicated in metastasis of several cancers." (PMID 32143622, 2020). "APOBEC3s are known to play to a role in cancer mutagenesis and APOBEC3G is highly expressed in colon cancer." (PMID 38903106, 2024). "Of note, APOBEC1 and APOBEC3A expression were only detected in a handful of cancers, such as APOBEC1 in PAAD, in contrast to APOBEC3G, which was detected in most cancer types." (PMID 36969056, 2023). "KRAS, IL-SAT5, and the Hedgehog signaling pathway were screened out based on APOBEC3G’s high expression, all of which were closely related to the development of cancer cells." (PMID 36144542, 2022). "Related studies have found that high expression of APOBEC3G can promote the occurrence and development of a variety of malignant tumors, including hepatocellular carcinoma, multiple myeloma and esophageal squamous cell carcinoma." (PMID 36339709, 2022). "APOBEC3G is highly expressed in various cancers and plays an essential role in regulating tumor growth and innate immune responses." (PMID 34025649, 2021). "Because the detailed function of APOBEC3G in cancer is still limited, we characterized its function in PDAC." (PMID 33669381, 2021). "APOBEC3G (A3G) has been found in several cancers; however, the role of A3G in SKCM is rarely studied." (PMID 32742470, 2020). "We also show that targeting APOBEC3G can sensitize cancer cells to radiation induced cell death by attenuating activation of the DNA repair pathway." (PMID 28903341, 2017). "The hub genes in modules with high correlation, such as ZAP70, RPS27A, GRP1, SLC39A1, APOBEC3G, and GZMA, could provide insights into the molecular mechanisms underlying cancer progression." (PMID 40395456, 2025). "Elevated APOBEC3G also contributed to increased homologous recombination activity, a mechanism that can utilize increased DNA breaks to mediate genomic rearrangements in cancer cells." (PMID 34625538, 2021). "Next, we confirmed a function of APOBEC3G in cancer progression, because sulforaphane or H19 knockdown subsequently decreased the expression of APOBEC3G, and APOBEC3G siRNA reduced cell viability, migration, invasion and tumor xenograft growth in our PDAC models." (PMID 33669381, 2021). "Since sulforaphane is known to inhibit TGF-β/Smad-induced EMT and thereby inhibit cancer progression, we analyzed whether APOBEC3G may influence TGF-β signaling." (PMID 33669381, 2021). "That the APOBEC3A, APOBEC3B, and APOBEC3G footprints are more abundant in comparison with the APOBEC1 and AID motifs suggests an important role for these three deaminases in generating somatic C:G>A:T mutations in human cancers." (PMID 30759888, 2019). "Interestingly, APOBEC3G was positively correlated with nRESs in multiple cancer types, such as CESC, PCPG, THYM, and MESO, but was negatively correlated in LAML, for unknown reasons." (PMID 36969056, 2023). "APOBEC3G mRNA regulation by EXOSC9 might also depend on the type of cancer." (PMID 32518284, 2020). "In addition, a role of APOBEC3G in disease progression and metastasis of PDAC is described, as well as in cancers of the colon, uterus, and cervix." (PMID 33669381, 2021). "Thus, we set 343 EXOSC9-target gene candidates including APOBEC3G in MDA-MB-231 cells as the “EXOSC9 target signature” and evaluated the correlation between this signature and cancer patient prognosis using the TCGA datasets." (PMID 32518284, 2020).
cancer (continued). "Apart from contributing to immunity against viral infection, recent studies suggested APOBEC3G also exerts important non-antiviral functions in cancer." (PMID 28903341, 2017).
tumor (31 papers, 2008 to 2025). "A study of tumor transcriptome data associated quantities of the long, non-coding RNAs SNHG5 and MIAT with EOC stage, while APOBEC3G expression in tumor infiltrating lymphocytes has been associated with EOC survival." (PMID 34449791, 2021). "APOBEC3G has been reported to be dysregulated in tumor tissues and is associated with the prognosis of multiple cancers." (PMID 34531901, 2021). "We show TGFβ signaling pathway regulated by APOBEC3G that was associated with enhanced tumor invasion in GBM." (PMID 28903341, 2017). "It is important to emphasize that within the prognostic model APOBEC3G behaves as a protective factor with potential anti-tumor action since higher APOBEC3G mRNA expression levels were associated with better clinical outcome in respect of OS." (PMID 27527602, 2016). "APOBEC3G, a DNA/RNA editing enzyme commonly associated with high mutational burden and tumor evolution, shows a strong positive correlation with the infiltration of B cells, CD8+ T cells, and dendritic cells in KIRC, implying a possible role in enhancing adaptive immune responses." (PMID 40977852, 2025). "Prior studies have linked several genes (LGALS8, PTPN12, YTHDC2, APOBEC3G, GPX3, RASA3, and TSPAN4) to immune responses, highlighting the impact of the tumor microenvironment (TME) on DCIS." (PMID 41020869, 2025). "We bioinformatically selected H19 candidate target genes and have chosen APOBEC3G as the top candidate gene due to its statistically relevant high correlation and a suggested interesting biological function as a virus-induced tumor promoter." (PMID 33669381, 2021). "We identified 103 common sulforaphane- and H19-related target genes and focused to the virus-induced tumor promoter APOBEC3G." (PMID 33669381, 2021). "The downregulation of the tumor promoter H19 and its target gene APOBEC3G was most significant and converged in inhibition of Smad2/TGF-β, which is involved in prevention of PDAC progression." (PMID 33669381, 2021). "In this study, we screened GICs and TCGA data and found that APOBEC3G was highly expressed in mesenchymal GBM; it was also associated with significantly decreased survival time in GBM patients, suggesting that it is a tumor-promoting factor in GBM." (PMID 28903341, 2017). "siRNA-mediated inhibition of H19 or APOBEC3G mimicked the tumor-inhibiting effect of sulforaphane." (PMID 33669381, 2021). "Importantly, APOBEC3G expression is upregulated by cytokine, tumor promoter, or mitogen stimulation and cytokine treatment of cells induced a shift of LMM APOBEC3G to its HMM conformation paralleled by increased susceptibility to HIV-infection." (PMID 18577210, 2008). "Staining the same TMA with an antibody that binds to APOBEC3A, APOBEC3B and APOBEC3G revealed characteristic nuclear APOBEC3B expression in tumour cells (Fig. EV4)." (PMID 39548236, 2025). "Based on the bio-information analysis, the transcriptional level of APOBEC3G was dramatically increased in AML compared to the control cohort, which is contrary to another tumor-related gene member APOBEC3B." (PMID 36144542, 2022). "The results showed that high APOBEC3G was most closely related to upregulating the KRAS signaling pathway, which played important roles in the cell cycle control of tumor initiation." (PMID 36144542, 2022). "High genomic alterations in zesto lesions were inversely correlated with putative tumor suppressor genes (MTUS2, DLGAP3, RTN1, CRLF1, SLC12A5, and PDIA2) and positively correlated with APOBEC mutagenesis (APOBEC3C, APOBEC3G, APOBEC3B, and APOBEC3F) and hypoxia-related gene signatures." (PMID 40319462, 2025). "In the TCGA-UCEC dataset, APOBEC3G, CUL4B, SCML2, TSPYL5, and ZBTB16 were significantly downregulated in tumor samples, whereas FOXP3, HJURP, HMGB3, and RAC3 were significantly upregulated in tumor samples, which was generally consistent with the result observed in GSE17025." (PMID 36936912, 2023).
tumor (continued). "While we identified APOBEC3G (A3G) dysregulation in SII ESCA, its role in imparting significant somatic hypermutations is currently unknown as A3G has been traditionally studied for its role in either providing immunity against a plethora of viruses or regulating tumour immune landscape." (PMID 38308202, 2024).
APOBEC3G also shares sentences with these, for which no sentence is quoted: leukemia (3 papers); acute myeloid leukemia (2); colon cancer (2); esophageal cancer (2); acute lymphoblastic leukemia (1); adult T-cell leukemia (1); autoimmune disease (1); B cell lymphoma (1); bacteremia (1); breast invasive carcinoma (1); Burkitt lymphoma (1); Cerebellar atrophy (1); cervical intraepithelial neoplasia (1); cholangiocarcinoma (1); chronic hepatitis B (1); Cirrhosis (1); clear renal cell carcinoma (1); colon adenocarcinoma (1); colorectal (1); colorectal tumors (1); cutaneous T cell lymphoma (1); glioblastoma (1); Hepatic fibrosis (1); hepatitis B virus infection (1); liver cancer (1); Lyme disease (1); metastatic melanoma (1); mumps (1); nevus (1); osteosarcoma (1).
A further 8 diseases each share a sentence with APOBEC3G in 1 paper.